NPRL2 (NPR2 like, GATOR1 complex subunit)
Diseases named in the same sentence as NPRL2 in open-access papers (continued):
Sharing a sentence is not in itself a finding about the gene and the disease.
cancer (16 papers, 2009 to 2025). A tumor composed of atypical neoplastic, often pleomorphic cells that invade other tissues. "There are fewer articles describing the role of NPRL3 and DEPDC5 in cancers, probably because NPRL2 has a higher cancer-associated mutation frequency among GATOR1 components." (PMID 41469472, 2025). "NPRL2 mutations can be found more often in different types of cancers and are associated with resistance to anticancer drugs cisplatin and doxorubicin." (PMID 34685669, 2021). "NPRL2 dysregulation has been implicated in many human pathologies, including cancers." (PMID 38915098, 2024). "NPRL2 has the higher cancer-associated recurrent mutational frequency out of all the GATOR1 genes." (PMID 34685669, 2021). "Previous studies functionally characterized NPRL2 and its molecular mechanism in cancer cells, but the role of NPRL2 in modulating the TME and its association with immune cells in tumors has not been previously studied." (PMID 39932765, 2025). "NPRL2 was also shown to induce apoptosis, inhibition of cell proliferation, and cell cycle arrest in many other cancer types." (PMID 39932765, 2025). "Constitutively active AKT signaling has been found in a variety of cancers which is downregulated by NPRL2." (PMID 39932765, 2025). "Our group along with others in different cancers previously reported that NPRL2 enhances sensitivity to chemotherapy and overcomes drug resistance." (PMID 39932765, 2025). "Nevertheless, many genes were downregulated in NPRL2−/− cells, known to be related to poor prognosis in various carcinomas and resistance to cisplatin." (PMID 41469472, 2025). "The GATOR1 complex, which consists of DEPDC5, Nprl2 and Nprl3, has GAP activity for RagA/B, and its inactivating mutations in cancers result in mTORC1 hyperactivation." (PMID 29199950, 2017). "Although NPRL2 is expressed in many normal tissues, inactivation of the NPRL2 gene has been found in many human cancers and cancer-derived cell lines, supporting a linkage to oncogenesis." (PMID 29127423, 2017). "Second, we predict that cancers with activating mutations in RHEB, or inactivating mutations in DEPDC5, NPRL2, and NPRL3, will show similar strong response to rapalogs." (PMID 26137524, 2015). "NPRL2 is located on the human chromosome 3p21.3 homozygous deletion region, a region that is deleted in various human cancers." (PMID 19521502, 2009). "NPRL2, a tumor suppressor gene, is downregulated or deleted in many cancers." (PMID 39932765, 2025). "Even though NPRL3 is a paralogue of NPRL2, its alternations in cancer are less recurrent." (PMID 34685669, 2021). "First, since NPRL2 overexpression inhibits cell proliferation, it might be of potential interest to explore a possibility to control NPRL2 expression in anti-cancer therapy." (PMID 29127423, 2017). "Thus, the effects of NPRL2 expression on mTOR may be especially important for cell survival and cell proliferation in the context of various cancers." (PMID 38915098, 2024). "Surprisingly, during the last decade, not a single article reported a study about the involvement of NPRL3 in cancer and drug resistance, even if in the COSMIC database there are almost three times more somatic cancer mutations listed for NPRL3 than for its paralogue NPRL2." (PMID 34685669, 2021). "According to the results obtained by Lerman & Minna, NPRL2/G21 may be one of the haploinsufficient genes that predispose to cancer in a hemizygous state and do not show a second mutation – or promoter hypermethylation – in the other allele (wild-type allele)." (PMID 26112163, 2015). "Further, as cancer cells with hyperactive mTORC1, either due to loss of PTEN or TSC1/2, have been shown to be particularly sensitive to rapamycin treatment, we speculate that cancer cells with mutated NPRL2 might also be particularly sensitive to rapamycin." (PMID 19521502, 2009).
cancer (continued). "NPRL2, along with NPRL3 and DEPDC5, forms the GATOR1 complex, an upstream regulator of the mTORС1, the function of which is perturbed in many cancers, particularly those resistant to cisplatin." (PMID 41469472, 2025). "We found that both EZH2-A and -B subtypes inhibited the expression of these four downstream cancer related genes (BMP2, PRODH, FOXO4, NPRL2), while EZH2-C exhibited the opposite effect." (PMID 39850359, 2025). "The study found a negative correlation among STAAD cancer patients between NPRL2 expression and PDCD1LG2, LAIR1, and BTLA checkpoint markers." (PMID 39932765, 2025). "The exact mechanism involved in the possible inactivation of NPRL2/G21 in human cancers has not been elucidated." (PMID 26112163, 2015).
neurologic disorders (2 papers, 2022 to 2024). "Missense and early-termination mutations in NPRL2 are associated with GATOR1-dependent neurological disease." (PMID 38396745, 2024).
NPRL2 also shares sentences with these, for which no sentence is quoted: breast carcinoma (3 papers); ovarian cancer (3); adenocarcinoma (2); infantile spasms (2); astrocyte tumors (1); autism (1); brain cancer (1); familial focal epilepsy with variable foci (1); febrile seizures (1); focal seizures (1); frontal lobe epilepsy (1); generalized tonic-clonic seizures (1); hemimegalencephaly (1); liver cancer (1); lung adenocarcinoma (1); sclerosis tuberous (1); sleep-related hypermotor epilepsy (1); small cell lung carcinoma (1); squamous cell lung carcinoma (1); temporal lobe epilepsy (1).